PPP2R2A (protein phosphatase 2 regulatory subunit Balpha)
Description:
Substrate-recognition subunit of protein phosphatase 2A (PP2A) that plays a key role in cell cycle by controlling mitosis entry and exit. Involved in chromosome clustering during late mitosis by mediating dephosphorylation of MKI67 (By similarity). Essential for serine/threonine-protein phosphatase 2A-mediated dephosphorylation of WEE1, preventing its ubiquitin-mediated proteolysis, increasing WEE1 protein levels, and promoting the G2/M checkpoint.
Synonyms: B55; PR52A; PR55A; B55A; PR55alpha; B55alpha
Tractability: PROTAC: ubiquitination databases record sites on it; its protein half-life has been measured; a small molecule that binds it is known.
Target class: Protein phosphatase regulatory subunit; Phosphatase; Enzyme; Protein Phosphatase
Gene: Protein-coding gene on chromosome 8 (26,291,508 to 26,372,680, forward strand). Ensembl gene ENSG00000221914.
Subcellular location (Human Protein Atlas): Cytosol
Pathways (Reactome):
Cell Cycle: Cyclin A/B1/B2 associated events during G2/M transition; Cyclin D associated events in G1; Initiation of Nuclear Envelope (NE) Reformation
Cellular responses to stimuli: Turbulent (oscillatory, disturbed) flow shear stress activates signaling by PIEZO1 and integrins in endothelial cells
Metabolism of RNA: Nonsense Mediated Decay (NMD) enhanced by the Exon Junction Complex (EJC)
Gene Ontology:
Molecular function: phosphoprotein phosphatase activity; protein binding; protein phosphatase regulator activity; enzyme-substrate adaptor activity; protein phosphatase 2A binding; protein-containing complex binding; tau protein binding
Biological process: protein dephosphorylation; regulation of chromosome segregation
Cellular component: protein phosphatase type 2A complex; protein serine/threonine phosphatase complex; cytosol; nucleoplasm; glutamatergic synapse; synapse
Genetic constraint (gnomAD): Loss-of-function variants: 7 observed, 36.15 expected, observed/expected ratio (o/e) 0.19, 90% interval 0.11 to 0.36. The upper end of that interval is the gene's LOEUF score, 0.36, which puts it in group 1 of 6, group 1 being the genes least tolerant of losing a copy. Missense variants: 185 observed, 441.6 expected, observed/expected ratio (o/e) 0.42, 90% interval 0.37 to 0.47. Synonymous variants: 137 observed, 145.51 expected, observed/expected ratio (o/e) 0.94, 90% interval 0.82 to 1.09.
Homologues: Orthologues: mouse Ppp2r2a (100% identical), rabbit PPP2R2A (100% identical), chimpanzee PPP2R2A (99% identical), pig PPP2R2A (99% identical), rat Ppp2r2a (99% identical), macaque PPP2R2A (99% identical), guinea pig PPP2R2A (99% identical), dog PPP2R2A (95% identical), tropical clawed frog ppp2r2a (94% identical), Caenorhabditis elegans sur-6 (66% identical). Paralogues in human: PPP2R2D (88% identical), PPP2R2B (85% identical), PPP2R2C (80% identical).
Diseases named in the same sentence as PPP2R2A in open-access papers:
PPP2R2A is named in the same sentence as 62 diseases in open-access papers, as found by Europe PMC text mining. Sharing a sentence is not in itself a finding about the gene and the disease. The quoted sentences say what the papers report.
breast carcinoma (25 papers, 2012 to 2025). "A study of 995 primary breast tumors identified heterozygous and homozygous deletions of the PPP2R2A gene associated with loss of B55α transcript in Estrogen Receptor (ER)-positive luminal B breast cancer." (PMID 33266510, 2020). "For luminal B subtype, PPP2R2A is an associated gene due to the dysregulation of specific PPP2R2A functions in luminal B breast cancers." (PMID 31874642, 2019). "PPP2R2A deletions were recently linked to a subgroup of luminal breast carcinoma (BC) that exhibits poor survival." (PMID 25879784, 2015). "In addition, heterozygous and homozygous deletions of PPP2R2A correlate with the loss of the PPP2R2A transcript in estrogen receptor-positive luminal B breast cancer." (PMID 39659585, 2024). "Importantly, a large cohort study revealed that deletion of PPP2R2A (the gene encoding the human B55 alpha subunit of PP2A) was often associated to breast cancer occurrence." (PMID 28041796, 2017). "Further Kaplan-Meier Plotter tools were used to analyze the correlation between the mRNA expression of PPP2R2A and Chk1 and the survival of patients with breast cancer." (PMID 36781846, 2023). "It is worth noting that breast cancer patients with high protein levels of pChk1-S317 or low levels of PPP2R2A show worse survival (P < 0.05)." (PMID 36781846, 2023). "To assess the clinical relevance of the PPP2R2A-Chk1 signaling axis, we next performed IHC staining to examine PPP2R2A and pChk1-S317 in serial sections of human primary breast cancer specimens (n = 137)." (PMID 36781846, 2023). "For example, PPP2R2A, the α isoform of B55 regulatory subunit family, is frequently deleted in luminal B breast cancers, which adds a significant pathophysiological feature to this cancer subtype." (PMID 35441157, 2022). "The percent of samples with decreased PPP2R2A mRNA expression in lung cancer, thyroid gland cancer, breast cancer and HCC were 36.82%, 94.44%, 65.21% and 58.82% respectively." (PMID 33588847, 2021). "The PPP2R2A gene is commonly deleted in human breast and prostate tumors, and PPP2R2A knockdown in breast cancer cell lines increases tumorigenicity." (PMID 32582689, 2020). "In particular, deletions in PPP2R2A, the gene encoding the α isoform of the PP2A regulatory subunit B55, are amongst the most frequent events in luminal-like breast cancer and define a sub-group of aggressive tumors." (PMID 29229993, 2018). "PPP2R2A is likely to correlate with luminal B since suggests the dysregulation of specific PPP2R2A functions in luminal B breast cancers." (PMID 29322925, 2017). "Here, we present the first study to evaluate PPP2R2A (B55α) expression in BC and show that CNA, namely deletions centered on PPP2R2A in the most recent TCGA Breast Cancer dataset, is associated with worse OS." (PMID 25879784, 2015). "An interesting gene in this pathway was the PPP2R2A gene (the only one located at 8p21.1), which is deleted at high frequencies in luminal type B breast cancer and non-small cell lung cancer, as well as being one of the most common breakpoints in prostate cancer." (PMID 39596687, 2024). "In addition, the survival analysis showed that breast cancer patients with lower PPP2R2A expression and higher pChk1-S317 expression had significantly worse survival." (PMID 36781846, 2023). "Notably, among those genetic alteration events whose loss enhances CDK4/6i sensitivity, CDK6, CCND3, CCNE1 and E2F3 were frequently amplified in the genomes of breast cancer patients, whereas among the genes whose loss promotes resistance, RB1, REXO2, PPP2R2A and STT3A were mainly depleted." (PMID 34508104, 2021). "Furthermore, a case-control study using haplotype analysis of tagged SNPs in the PPP2R2A (coding for PP2A-Bα) and PPP2R1A (coding for PP2A-Aα) genes demonstrated that certain genotypes were protective for breast cancer, while others modified the risk for women with proliferative breast lesions." (PMID 22539979, 2012).
breast carcinoma (continued). "In addition to mutations in the scaffold subunits, B55α (encoded by the PPP2R2A gene) and B55β (encoded by PPP2R2B) subunits are occasionally eliminated by deletion or hypermethylation of the corresponding genes suggesting the relevance of PP2A-B55 activity in preventing breast cancer development." (PMID 29229993, 2018). "In breast carcinoma (BC), the expression status and genomic alterations of PP2A and it subunits, such as PPP2R2A, are only now being elucidated." (PMID 25879784, 2015). "For example, RAR-L3 (8p21.2) and RAR-L5 (17p12), where PPP2R2A and MAP2K4 are located, respectively, and RAR-G13 (17q12), where ERBB2 is located, were consistently detected in a recent large-scale breast cancer genetic subgroup study." (PMID 22938721, 2012). "Taken together, these data reveal a negative correlation between PPP2R2A and pChk1-S317, highlighting the clinical relevance of PPP2R2A–Chk1 signaling axis in the progress of patients with breast cancer." (PMID 36781846, 2023). "The roles of PDPK1, PKN2, PPP2R2A, and PPP2R5E in PI3K pathway regulation of HER2+ breast cancer progression and inhibition by PGB-0-ol remain unclear." (PMID 38028209, 2023). "Although we did not directly demonstrate the loss of B55α immunoreactivity in cases with known deletions of the chr 8p21.2 region, we show that in the TCGA Invasive Breast Cancer Dataset there is a strong correlation between CNA and PPP2R2A (B55α) mRNA expression in 736 BCs." (PMID 25879784, 2015). "Copy number aberrations (CNAs) in known breast cancer driver genes present in the PDTXs included gains/amplifications of MYC (78%), CCNE1 (34%), ZNF703 (25%), CCND1 (31%), MDM2 (25%), and ERBB2 (9%) and deletions of PTEN (41%), PPP2R2A (72%), CDKN2A (47%), and CDKN2B (47%)." (PMID 27641504, 2016). "PPP2R2A appears to be a tumor suppressor gene that is frequently absent or under-expressed in most human tumors, such as prostate cancer, ovarian cancer, acute myelocytic leukemia (AML), and breast cancer, pointing that PPP2R2A may play a role in tumorigenesis." (PMID 36781846, 2023). "We next analyzed the expression of PPP2R2A and Chk1 with tumor stage of breast cancer using GEPIA database, and found that Chk1 group varied significantly among tumor stage of breast cancer but not the PPP2R2A group." (PMID 36781846, 2023).
lung cancer (18 papers, 2010 to 2025). A malignant neoplasm involving the lung. "PPP2R2A+/- cancer cells have enhanced sensitivity to PD-L1 blockade in a mouse model of lung cancer due to modulation of the tumor immune microenvironment, resulting in increased NK cells and reduced infiltration and function of Tregs." (PMID 41411055, 2025). "For example, it has been demonstrated that PPP2R2A promotes tumorigenesis and metastasis in pancreatic cancer cells 37 but inhibits metastasis in lung cancer." (PMID 39659585, 2024). "For example, miR-31 was demonstrated that overexpression of miR-31 led to increased growth rate by targeting suppressors, LATS2 and PPP2R2A in lung cancer." (PMID 25797269, 2015). "Such modulation of the LATS2/PPP2R2A pathway by miR-31 constitutes a novel growth regulator in lung cancer." (PMID 24744457, 2014). "It inhibits cell growth and tumorigenicity by directly repressing the tumour suppressor large tumour suppressor kinase 2 (LATS2) and protein phosphatase 2 regulatory subunit B α (PPP2R2A), establishing a novel regulatory network in lung cancer via the miR-31-LATS2-PPP2R2A pathway." (PMID 40430112, 2025). "PPP2R2A knockdown leads to increased sensitivity to PARP inhibition in lung cancer." (PMID 39659585, 2024). "Also, HeLa cells treated with shRNAs specific for PPP2R2A and lung carcinoma cell lines with intrinsically decreased levels of PPP2R2A showed increased sensitivity to Veliparib in comparison to their respective controls." (PMID 27642590, 2016). "More recently, factor-inhibiting hypoxia-inducible factor (FIH) was experimentally verified as the target of miR-31 in HNSCC cell and the tumor-suppressive genes, large tumor suppressor 2 (LATS2) and PP2A regulatory subunit B alpha isoform (PPP2R2A) were the targets of miR-31 in lung cancer." (PMID 21062447, 2010). "Three DEGs shared the common pathways like CDKN20 in non‐small cell lung cancer and viral carcinogenesis, CDC20 in ubiquitin mediated proteolysis and viral carcinogenesis and PPP2R2A in Adrenergic signalling in cardiomycytes." (PMID 39434198, 2024). "In colon cancer, esophageal neoplasia, and lung cancer, miR-31 acts as an oncogenic miRNA by inhibiting the expression of E2F2, STK40, and PPP2R2A, respectively." (PMID 28783765, 2017). "On the contrary, miR-31 acts as an oncogenic miRNA in human lung cancer tissues by targeting specific tumor suppressors LATS2 (large tumor suppressor kinase 2) and PPP2R2A (protein phosphatase 2, regulatory subunit B, alpha)." (PMID 29152108, 2017). "The oncogenic effects of miR-31 in lung cancer cells were attributed to inhibition of large tumor suppressor 2 (LATS2) and PP2A regulatory subunit B alpha (PPP2R2A)." (PMID 21048943, 2010). "For example, BMPR2, BRD7, PRKAG2, PRKAR1A and PPP2R2A (PP2A Bα subunit B55α), which are differentially expressed between group V (H+V−S+[M/T]) and groups II/IV (H+V+S−/H+V−S+[M]), play roles in tobacco-mediated lung diseases and lung cancers." (PMID 35642061, 2022). "Some studies have shown that the expression of hsa-mir-139-5p in human lung cancer cell lines inhibits the activity of DICER1, but does not inhibit PPP2R2A or LATS2." (PMID 35794555, 2022).
pancreatic cancer (12 papers, 2016 to 2025). "Accordingly, PPP2R2A expression is associated with poor survival in pancreatic cancer." (PMID 36358647, 2022). "miR-590-3p directly downregulates p27 and PPP2R2A and, through the G1/S cell cycle pathway, promotes pancreatic cancer development." (PMID 41095675, 2025). "MiR-590-3p by directly inhibiting p27 and PPP2R2A could promote the development of pancreatic cancer via the G1/S cell cycle pathway." (PMID 33330110, 2020). "However, only 20% of PPP2R2A mRNA expression was reduced in pancreatic cancer." (PMID 33588847, 2021). "However, in CRC, pancreatic cancer and GBM, PP2A complexes containing PPP2CA and PPP2R2A form part of a positive feedback loop contributing to its activation." (PMID 36358647, 2022).
non-small cell lung carcinoma (9 papers, 2015 to 2025). A group of at least three distinct histological types of lung cancer, including non-small cell squamous cell carcinoma, adenocarcinoma, and large cell carcinoma. "PP2A B55α, a regulatory subunit of protein phosphatase 2 (PP2A), is underexpressed in greater than 40% of non-small cell lung cancer (NSCLC) cases due to loss of heterozygosity of PPP2R2A, the gene encoding this protein." (PMID 41411055, 2025). "A recent study reported an association between PP2A B-regulatory subunit (PPP2R2A) deficiency and Chk1 inhibition in non-small cell lung cancer." (PMID 36781846, 2023). "A recent study showed that PPP2R2A deficiency makes non-small cell lung cancer cells more sensitive to Chk1 inhibition." (PMID 36781846, 2023). "PP2A B55α, encoded by PPP2R2A, is a regulatory subunit of the serine/threonine protein phosphatase 2 (PP2A) that influences CHK1 sensitivity in non-small cell lung cancer (NSCLC)." (PMID 39659585, 2024). "Nevertheless, also BRCA-independent defects in HR-mediated DNA repair e.g. by downregulation of protein phosphatase 2 regulatory subunit B alpha (PPP2R2A) in non-small cell lung cancer cells promoted increased sensitivity to PARP inhibitors in vitro and in vivo." (PMID 29221109, 2017).
prostate carcinoma (8 papers, 2015 to 2025). A carcinoma that arises from epithelial cells of the prostate gland. "LCMT1 methylates the C-terminal leucine of PPP2R2A to regulate PP2A substrate specificity and has been implicated in prostate cancer through AR regulation." (PMID 40493189, 2025). "For example, the PPP2R2A gene, which codes for the regulatory subunit B55α, is deleted in breast and prostate carcinomas and myelomas." (PMID 25699237, 2015). "After the studies included in this analysis were initiated, data from the PROfound study demonstrated that no benefit of olaparib over control therapy was observed in patients with prostate cancer and PPP2R2A mutations and was not predictive of benefit from PARP inhibitor therapy." (PMID 39695768, 2024).
breast tumors (6 papers, 2015 to 2024). "Moreover, deletions in PPP2R2A (gene encoding B55α isoform) are frequently detected in prostate and breast tumours and the promoter silencing of PPP2R2B (gene encoding B55β isoform) has been found in colorectal cancer." (PMID 26613407, 2015). "We found the level of PPP2R2A was lower in rat breast tumor than in the spleen tissues, and the level of pChk1-S317 was higher in the breast tumor than in the spleen tissues (P < 0.01)." (PMID 36781846, 2023). "We observed the expression of PPP2R2A and pChk1-S317 in serial sections by IHC staining, the combination of VPA and HU significantly enhanced the PPP2R2A level but decreased the pChk1-S317 level in breast tumor tissues (P < 0.01)." (PMID 36781846, 2023). "The analysis indicated a negative correlation between pChk1-S317 expression and PPP2R2A expression was also consistently observed in human primary breast tumor tissues (P < 0.01)." (PMID 36781846, 2023).
ovarian carcinoma (6 papers, 2013 to 2024). A malignant neoplasm originating from the surface ovarian epithelium. "For instance, 57.14% of ovarian cancers have reduced expression of PPP2R2A with most cases caused by PPP2R2A loss of heterozygosity." (PMID 39659585, 2024). "A bioinformatic analysis of ovarian cancer tumors predicted that loss of PPP2R2A occurs early in ovarian tumor progression." (PMID 31822657, 2019). "Thus, PPP2R2A expression is frequently downregulated in ovarian cancer, which is strongly associated with a poor prognosis." (PMID 39659585, 2024). "Targeting ovarian cancer cells with a deficiency in PPP2R2A presents an unmet clinical need." (PMID 39659585, 2024). "Therefore, it is crucial to determine the impact of PPP2R2A deficiency in ovarian cancer." (PMID 39659585, 2024). "According to the analysis of three TCGA data sets from cBioportal, we found that PPP2R2A expression is lower or deeply deleted in approximately 30% of ovarian cancer." (PMID 39659585, 2024). "miR614 expression is also increased in ovarian cancer patients and a subset of ovarian cancer cell lines, in which miR614 promotes proliferation by suppressing the expression of the phosphatase PPP2R2A." (PMID 33374314, 2020). "Finally, PPP2R2A is involved in ovarian cancer biology and ZEN exposure promotes tumorigenesis in granulosa cells." (PMID 38666409, 2024). "Of the mutator genes identified in our analysis of lung and ovarian cancer, BRCA1/2, PRKDC, and PPP2R2A gene in the region 8p21.2 belong to this category although the role of PPP2R2A in inducing chromosomal instability in ovarian cancer was previously unknown." (PMID 24330428, 2013). "PPP2R2A/PP2A B55α is frequently deleted or under-expressed in various human cancers, including ovarian cancer." (PMID 39659585, 2024). "Although tumor suppressor activity of PPP2R2A has not been demonstrated in ovarian cancer, our data suggests that this may be likely." (PMID 31822657, 2019).
acute myeloid leukemia (4 papers, 2015 to 2025). Acute myeloid leukemia (AML) is a group of neoplasms arising from precursor cells committed to the myeloid cell-line differentiation. "Furthermore, in patients with acute myeloid leukemia (AML), low levels of B55α expression in blast cells have been associated with shorter complete remission duration, demonstrating that in AML, the decreased expression of PPP2R2A (B55α) is an adverse prognostic factor." (PMID 25879784, 2015).